ENSG00000254692 (novel protein)
Gene: Protein-coding gene on chromosome 14 (24,189,157 to 24,213,473, reverse strand). Ensembl gene ENSG00000254692.
Genetic constraint (gnomAD): Loss-of-function variants: 51 observed, 81.16 expected, observed/expected ratio (o/e) 0.63, 90% interval 0.5 to 0.79. Missense variants: 833 observed, 1,082.5 expected, observed/expected ratio (o/e) 0.77, 90% interval 0.73 to 0.81. Synonymous variants: 374 observed, 416.44 expected, observed/expected ratio (o/e) 0.9, 90% interval 0.82 to 0.98.